FOXP3 (forkhead box P3)
Diseases named in the same sentence as FOXP3 in open-access papers (continued):
Sharing a sentence is not in itself a finding about the gene and the disease.
leprosy (continued). "Flow cytometry results showed that the expression of FoxP3 in CD4+CD25+ cells Treg significantly increased (p < 0.0005) when leprosy derived (BT, BL/LL) CD19+ B cells cocultured with Tregs (CD4+CD25+)." (PMID 30083152, 2018). "Cell coculture experiments also demonstrated that leprosy derived IL-10 producing Bregs enhance FoxP3 and PD-1 expression in Tregs and enhanced Tregs activity." (PMID 30083152, 2018). "While FoxP3 expressing Treg producing TGF-β are increased in stable lepromatous leprosy patients, patients with reactions exhibit an imbalance in Th17 and Treg populations." (PMID 28162092, 2017). "A study in leprosy revealed that FoxP3+ Treg cells that produce TGF-β down regulate the T cell responses and results in the characteristic antigen specific anergy observed in LL cases." (PMID 26751584, 2016). "MFI of FOXP3 decreased sequentially in CD25hi CD25low and CD25neg populations of all 3 clinical types and showed discrimination between the leprosy types." (PMID 24454972, 2014). "CD8+ population of T cells with CD25+FOXP3+ were lower than the CD4+ T cells in both leprosy types and healthy contacts." (PMID 24454972, 2014). "Gene expression (Mean (ΔCt ± SD) of selected cytokines, signaling molecules and transcription factors associated with FOXP3+Treg and iTreg cells in skin lesions and M.leprae stimulated PBMC respectively in leprosy patients and healthy subjects." (PMID 24454972, 2014). "Healthy contacts with long time exposure to leprosy patients also showed expression of FOXP3 and inhibitory cytokines to a lesser extent." (PMID 24454972, 2014). "It has been reported that CD25neg cells show transient expression of low FOXP3 which is in agreement with our study in leprosy." (PMID 24454972, 2014). "To further characterize the nature of FOXP3+ cells we undertook flowcytometry analysis both in leprosy and house hold contact subjects." (PMID 24454972, 2014). "In this study, we have investigated the functional role of CD25+ Treg cells in M. leprae unresponsiveness of LL patients as well as the frequency of CD25+ and FoxP3+ cells in the PBMC of leprosy patients." (PMID 24722473, 2014). "Skin lesions of both tuberculoid and lepromatous leprosy patients showed the presence of nuclear FOXP3+ staining using immunohistochemistry." (PMID 24454972, 2014). "Further studies are required to formally establish the functional nature of such FOXP3 cells in leprosy." (PMID 24454972, 2014). "TCRγδ + FoxP3 + cells and their role during disease progression in leprosy patients." (PMID 39308868, 2024). "Taken together our results indicated that PD-1 expression on CD4+CD25+FoxP3+ cells increased in leprosy patients, it may contribute to immunosuppression of the host." (PMID 37153623, 2023). "According to a study conducted on leprosy patients, FoxP3+ Treg cells have been shown to down-regulate T cell responses, which results in both the characteristic antigen-specific anergy in leprosy patients and the characteristic leprosy-induced symptoms of inflammation." (PMID 37153623, 2023). "The epigenetics behind disease progression in leprosy was also investigated in interactions of FOXP3 with histone deacetylases (HDACs) and histone acetyl transferases (HATs) that activate/inactivate transcription by inducing the transfer of an acetyl group to the histone core." (PMID 35722339, 2022). "Different levels of FOXP3 TSDR methylation in Tregs of different leprosy clinical forms may be a marker for prognosis and disease progression." (PMID 35722339, 2022). "Natural Tregs (CD25+FOXP3+ cells) are intended to maintain tolerance, suppressing the function of autoreactive T cells in different skin diseases, and have been studied for their involvement in various diseases, including leprosy." (PMID 34748560, 2021). "FoxP3+ decrease TH1, which may cause bacilli to survive and become distributed in these types of leprosy in patients with MB." (PMID 33573064, 2021).
leprosy (continued). "However, TGF-β is associated with FOXP3+ Treg differentiation and stability and also our previous study have already reported that TGF-β is low in T1R as compared to NR leprosy patients." (PMID 32934336, 2020). "Our study evaluated the in situ expression of both double positive CD25+ Foxp3+ Treg cells and cytokines in leprosy T1R and T2R with special emphasis on the frequency of Treg cells in paired biopsies collected in the absence of reaction and during the course of a reactional episode." (PMID 29883464, 2018). "Moreover, CD19+ B cells of leprosy patients (BL/LL) also induces FoxP3, PD-1 expression as well as also induced IL-10 and TGF-β immunosuppressive cytokines expression in T effector cells." (PMID 30083152, 2018). "IL-10 was also increased in the culture supernatants of lepromatous as compared to tuberculoid leprosy patients (p<0.02) In general, increase in FOXP3+ cells in leprosy is in agreement with other studies in leprosy; however there are differences in the nature of cytokine associated with them." (PMID 24454972, 2014). "Recently, the mechanism of action of FoxP3 in CD4+CD25+ T cells derived from BL/LL leprosy patients was shown to result from increased molecular interactions of FoxP3 with Histone deacetylases (HDAC7/9) in the nucleus of CD4+CD25+ T cells derived from BL/LL patients." (PMID 24722473, 2014). "Therefore, the objective of this study was to investigate the expression of FOXP3+ Treg cells in leprosy skin lesions and to correlate their clinical forms, laboratory characteristics (CD4, CD8, and CV), and the immune reconstitution syndrome in HIV-leprosy co-infection." (PMID 34748560, 2021). "This study aimed to elucidate a few of these gaps by exploring the role of FOXP3-positive regulatory T cells (Tregs) on the immune response during leprosy co-infection with HIV, by comparing the response of patients with leprosy based on whether or not they present a HIV and leprosy reaction." (PMID 34748560, 2021). "FoxP3 positive regulatory T cells (Treg) producing TGF-β can suppress effector T cell function and were increased in stable lepromatous patients, which may explain the anergy associated with this leprosy clinical form." (PMID 28162092, 2017). "It is of interest that FOXP3+ iTreg cells were higher in healthy contacts (p<0.001) as compared to tuberculoid leprosy suggesting that dampening of immune responses during early stages of infection may help in protection from clinical disease akin to the dynamic state noted in dermal leishmaniasis." (PMID 24454972, 2014). "The real-time PCR assay of FoxP3 and PD-1 further supported the findings that CD19+ cells of leprosy patients have capacity to convert the T effector cells into Tregs." (PMID 30083152, 2018). "This study investigated the in situ expression of CD25+Foxp3+ Treg cells and TGF-β1, IFN-γ, IL-17 in leprosy T1R and T2R." (PMID 29883464, 2018). "We found an increased frequency of Bregs and increased expression of their immune modulatory molecules (IL-10, FoxP3, and PDL-1) in leprosy patients." (PMID 30083152, 2018). "TGF-β is known to induce FoxP3 expression in Tregs and others immune cells and high TGF-β level has been reported in leprosy patients, thus we examined the FoxP3 expression in CD19+IL-10+ cells derived from leprosy patients and healthy controls." (PMID 30083152, 2018). "In order to identify the Treg cells in human leprosy, immunophenotyping was done for the markers CD4, CD25 and FoxP3 on PBMCs derived from leprosy patients (BT/TT vs. BL/LL) (n = 15 in each group) and healthy contacts (HCs, n = 10)." (PMID 26751584, 2016). "In both types of reactions, CD4+CD25+ Treg cells showed significant reduction in MFI of FOXP3 in antigen stimulated PBMC of (p<0.02, p<0.003) though qPCR showed an increase in its expression as compared to stable non reactive lepromatous leprosy patients." (PMID 27035913, 2016).
leprosy (continued). "In the circulation of leprosy patients, both CD4+Foxp3+ and CD8+Foxp3+ T-cells were almost twofold increased compared to healthy contacts." (PMID 26029205, 2015). "Both skin lesions as well as in vitro antigen stimulated PBMC showed increased percentage/mean fluorescence intensity of cells and higher gene expression for FOXP3+, TGF-β in lepromatous (p<0.01) as compared to tuberculoid leprosy patients." (PMID 24454972, 2014). "This was consistent with previous findings that IL-17, IFN-γ, and Foxp3 levels from PBMC showed increase in patients with leprosy reactions compared with non-reactions leprosy patients." (PMID 36389696, 2022). "FOXP3+ T cells have been described in the blood and skin lesions of leprosy patients; however, there is no consensus in the literature on the role of Tregs in the disease." (PMID 35722339, 2022). "This explains the significant difference in FOXP3+ levels in leprosy patients in endemic areas and healthy patients in nonendemic areas, where lower FOXP3+ is consistently found in the healthy mother populations in nonendemic areas." (PMID 33708252, 2021). "To date, it is known that in co-infected patients, the frequency of FOXP3+ cells does not seem to be influenced by the clinical type of leprosy, the CD4+ T cell count in the peripheral blood, or the HIV viral load." (PMID 34748560, 2021). "The unsignificant difference in IL-17 and FOXP3+ was found between healthy populations (mother and children) on leprosy-endemic areas (group D) and healthy populations on nonendemic areas (group E) in this study." (PMID 33708252, 2021). "We investigated the dysregulation of immune system by comparing IL-17 and FOXP3+ levels occurring in maternal and child leprosy patients in endemic and nonendemic areas." (PMID 33708252, 2021). "It was suggested that the frequency of FOXP3+ cells in the skin was not influenced by the clinical type of leprosy, CD4+ T cell count, or HIV viral load." (PMID 34748560, 2021). "FoxP3, the main marker of Treg cells, has been found in various forms of leprosy, with and without leprosy reactions." (PMID 33573064, 2021). "The close relation between transmission and dysregulation of body immunity prompted the authors to conduct a study on differences in levels of IL-17 and FOXP3+ in leprosy patients in endemic and nonendemic areas, especially in female and pediatric patients." (PMID 33708252, 2021). "The higher frequency of CD19+IL-10+ Breg cells with increased expression of FoxP3 and PDL-1 on Bregs suggests that increased in FoxP3 and PDL-1 expression by the Breg cells might be instrumental in dampening of the T cell function in leprosy patients." (PMID 30083152, 2018). "The role of FOXP3+ regulatory T cells (Treg) during leprosy reactions was investigated using both qPCR and flow cytometry analysis of ex vivo stimulated PBMC from both stable and matching leprosy reaction groups." (PMID 27035913, 2016). "For example, the recent molecular analysis of FoxP3 in CD4+CD25+ T cells nuclei has revealed that the FoxP3 interaction with histone deacetylases drives the immune suppression by CD4+ CD25+ Tregs in BL/LL unlike in other forms of leprosy." (PMID 24722473, 2014). "Although the suppressive potential of Treg and the relation with FOXP3 expression has not been investigated in leprosy, the FOXP3 expression was more related with Treg suppressive potential than the Treg frequency in mice." (PMID 24244424, 2013). "Anti-CD28/CD49d were used in all the culture of mononuclear cells as costimulatory molecules and to test whether Tregs influence development of leprosy reactions, we analyzed CD4+ and CD8+ Treg cells, defined as CD25+Foxp3+, in multibacillary patients, T1R, T2R and HV." (PMID 35924037, 2022). "Using flow cytometry, the present study confirmed the increase in inhibitory FOXP3+Treg cells and TGF-β+ cells in stable non reactive lepromatous leprosy patients which may be related to the T cell unresponsiveness observed in this form of leprosy." (PMID 27035913, 2016).
leprosy (continued). "CD4+CD25+FOXP3+ T cells (Tregs) were increased in unstimulated basal cultures (p<0.0003) and showed further increase in in vitro antigen but not mitogen (phytohemaglutinin) stimulated PBMC (iTreg) in lepromatous as compared to tuberculoid leprosy patients (p<0.002)." (PMID 24454972, 2014). "Taken together, our studies show an increase in TGF-β+ CD4+ CD25+ FOXP3+ T cells both in dermal lesions and in in vitro induced antigen but not mitogen stimulated PBMC (iTreg) of lepromatous leprosy patients." (PMID 24454972, 2014). "Differences between the two clinical types of leprosy were only observed with TGF-β producing CD4+T cells which had CD25+FOXP3+ phenotype (p<0.002) and not with FOXP3+ cells alone or where CD25 was absent." (PMID 24454972, 2014). "In the sample studied, there was a positive correlation between FOXP3+ cell density and viral load, negative correlation with blood CD4+ (not statistically significant), significant positive correlation in CD8 count in patients with leprosy reaction, and positive relationship in patients with IRIS." (PMID 34748560, 2021).
autoimmune thyroid disease (21 papers, 2011 to 2025). Inflammatory disease of the thyroid gland due to autoimmune responses leading to lymphocytic infiltration of the gland. "Future research should aim to validate these findings in larger, multiethnic cohorts and explore the mechanistic links between FOXP3 variants, Treg dysfunction, and thyroid autoimmunity." (PMID 40109804, 2025). "Furthermore, polymorphisms of FOXP3 play a role in genetic susceptibility to autoimmune thyroid diseases, and the genotype of FOXP3 was reported to have an association with the severity of Hashimoto’s disease." (PMID 29884162, 2018). "It will be of great interest to dive deeper into the possible link of certain Foxp3 polymorphisms and thyroid-specific antibodies, to facilitate our understanding of the immune regulation at a molecular level as well as Tregs-related pathogenesis that occur during autoimmune thyroid diseases." (PMID 32612577, 2020). "Joint susceptibility genes identified for T1DM and autoimmune thyroid diseases, including hypo- or hyperthyroidism, are HLA class II genes, PTPN22, CTLA-4 and FOXP3." (PMID 38116309, 2023). "Interestingly, thyroid autoimmunity in TS has been mapped to a critical region in Xp11.2–p22.1, the chromosomal region containing the FOXP3 gene." (PMID 26709833, 2015). "Studies in autoimmune thyroid models show reduced CD4+CD25+Foxp3+ cell numbers and decreased Foxp3 mRNA expression in splenocytes." (PMID 41383597, 2025). "In children with autoimmune thyroid diseases, the CD4+ CD25hi CD127low FOXP3+ sub-population was shown to be significantly reduced compared to healthy donors, while there was no significant change in the CD4+ CD25hi CD127low sub-population." (PMID 40804844, 2025). "Moreover, these Tregs had a significantly higher ability to maintain Foxp3 expression when activated in the presence of IL-1β, which enhanced their capacity to suppress the effector T cell response in vitro and ongoing experimental autoimmune thyroiditis in vivo." (PMID 33643294, 2020). "This study aimed to compare the number of CD4/CD25/FOXP3 T regulatory cells in the different forms of autoimmune thyroid diseases and in the normal population, and to compare the number of CD4 + CD25 + FOXP3 + T regulatory cells between the different forms of AITD, HT, and GD." (PMID 41307767, 2025). "This study aimed to compare the number of CD4/CD25/FOXP3 T regulatory cells between the different forms of autoimmune thyroid diseases from one hand, and to compare the number of CD4 + CD25 + FOXP3 + T regulatory cells between the different forms of AITD and a control group on the other hand." (PMID 41307767, 2025). "The genes responsible for autoimmune thyroid diseases could be categorized as either thyroid-specific types (e.g., thyroglobulin and TSH receptor) or immune-modulating types (e.g., Forkhead box P3 (FOXP3), CD25, CD40, CTLA-4, and HLA)." (PMID 29884162, 2018). "The frequency of FOXP3+ Tregs among CD4+ T cells was significantly higher in the patients with TS than in the HC regardless of the presence of thyroid autoimmunity." (PMID 26709833, 2015). "In contrast, FOXP3+Treg lymphocytes play a nonredundant role in the protection against thyroid autoimmunity, as Treg depletion was shown to induce a Th1-dependent form of EAT in mice, while diminished Treg cell numbers and attenuated FOXP3 gene expression were found in PBMC of HT patients." (PMID 27478306, 2016).